SLPI (secretory leukocyte peptidase inhibitor)
Diseases named in the same sentence as SLPI in open-access papers (continued):
Sharing a sentence is not in itself a finding about the gene and the disease.
keloid (1 paper, 2021). An irregularly shaped, elevated mark on the skin caused by deposits of excessive amounts of collagen during wound healing. "By comparing the data with the keloids ECMs, we found some of the components, e.g., SLPI, THBS3, show both high expression trends in keloids and in elderly skin, indicating these ECMs could share similar functions in elderly and keloids skin tissue." (PMID 34901026, 2021).
kidney damage (1 paper, 2014). "Furthermore SLPI urine concentration was highly correlated with SLPI gene expression in the organ, indicating a link of elevated SLPI concentration in urine to the status of kidney damage in the organ itself." (PMID 25093671, 2014).
kidney injury (1 paper, 2023). Trauma to the kidney. "As an inhibiting proteolytic enzyme, SLPI involves in immune functions of MSC to control T-cell proliferation and the regulation of damaged tissue healing, and was also identified as an ideal biomarker for kidney injury." (PMID 38027143, 2023).
Lewis lung carcinoma (1 paper, 2025). "In Lewis lung carcinoma, TNF-α was found to induce SLPI expression, suggesting a feedback mechanism where SLPI modulates TNF-α’s inflammatory effects." (PMID 40284680, 2025).
Lyme disease (1 paper, 2025). Lyme disease (named after the towns in the USA where the disease was first identified) is a bacterial infection caused by Borrelia burgdorferi. "Based on our data obtained from the Slpi-deficient mice, we assessed the serum SLPI level in Lyme disease patients." (PMID 40392222, 2025).
malaria (1 paper, 2018). Malaria is a serious and sometimes fatal disease caused by a parasite that commonly infects a certain type of mosquito which feeds on humans. "SLPI is also up-regulated in the malaria severity signature." (PMID 29642892, 2018).
Netherton syndrome (1 paper, 2020). Netherton syndrome (NS) is a skin disorder characterized by congenital ichthyosiform erythroderma (CIE), a distinctive hair shaft defect (trichorrhexis invaginata; TI) and atopic manifestations. "Building on previous work showing the clinical potential of targeting Klk5 in Netherton syndrome, our work establishes KLK7 and ELA2 as promising targets for the treatment of Netherton syndrome patients through the activation of NRF2 and subsequent upregulation of SLPI." (PMID 32457102, 2020).
neutropenia (1 paper, 2021). A decrease in the number of neutrophils found in the blood. "This study, for the first time, suggests that in addition to neutropenia, the aberrant levels and functions of ELANE, SLPI and their downstream molecules in pulp cells play an important role in oral complications in SCN patients." (PMID 34580954, 2021). "In addition to neutropenia that leads to oral infection, we show that severely downregulated neutrophil activity and ELANE and SLPI expression in dental cells could be involved in orodental infections." (PMID 34580954, 2021).
osteosarcoma (1 paper, 2024). A usually aggressive malignant bone-forming mesenchymal neoplasm, predominantly affecting adolescents and young adults. "Specifically, the EMT score of S100A1+ cells were significantly higher than that of TMSB4X+ and SLPI+ cells, suggesting that osteosarcoma cells in the TMSB4X+ cells exhibit a greater migration ability, possibly associated with an increased propensity for metastasis." (PMID 39742274, 2024).
otitis media (1 paper, 2025). Inflammation of the anatomical structures of the middle ear, which is most often caused by an infectious process. "Given the role of SLPI in immune modulation and host defense in mucosal epithelia, our findings support the SLPI variant as modulating susceptibility to otitis media." (PMID 40003878, 2025). "In bulk mRNA-seq data from an independent cohort of children with otitis media, SLPI was co-expressed with genes involved in infection, immune response, inflammation, and epithelial cell organization." (PMID 40003878, 2025).
ovarian tumors (1 paper, 2009). "Several ovarian biomarkers, such as Kallikreins, osteopontin, leptin, HE-4, LPA, MUC1 and SLPI, have been identified in the past several years through various approaches, including gene expression profiling and proteomics analysis of ovarian tumors." (PMID 19619303, 2009).
pancreatic adenocarcinoma (1 paper, 2007). "These genes include many not previously associated with pancreatic adenocarcinoma, such as galectin-4 (LGALS4), mucin 13 (MUC13), secretory leukocyte protease inhibitor (SLPI), collagen 17A1 (COL17A1), and ropporin 1-like (ROPN1L)." (PMID 17389914, 2007).
pelvic organ prolapse (1 paper, 2022). Abnormal descent of a pelvic organ resulting in the protrusion of the organ beyond its normal anatomical confines. "For example, secretory leukocyte protease inhibitor (SLPI) and elafin confer protease inhibition activity which plays an important role in tissue integrity and low expression of elafin is associated with pelvic organ prolapse and urinary stress incontinence." (PMID 36077500, 2022).
Pleural effusion (1 paper, 2021). The presence of an excessive amount of fluid in the pleural cavity. "For the differential diagnosis of early-stage MPM, we propose the inclusion of SLPI as a pleural effusion marker along with CYFRA21-1." (PMID 34155270, 2021). "SLPI levels in the pleural fluid of patients with BAPE were significantly lower than those in patients with MPM, LCa, and other pleural effusions (p < 0.0001)." (PMID 34155270, 2021).
pyometra (1 paper, 2015). "The SLPI gene identified as the top overexpressed gene in pyometra encodes an antimicrobial peptide secreted by epithelial tissues." (PMID 26222498, 2015). "The SLPI (secretory leukocyte peptidase inhibitor) gene was detected as having the highest fold change, being 30 times more expressed in pyometra compared with other endometrial tissues." (PMID 26222498, 2015). "SLPI, PTGS2/COX2, MMP1, S100A8, S100A9 and IL8 were among the top up-regulated genes detected in pyometra, further confirmed by external expression data." (PMID 26222498, 2015).
renal dysfunction (1 paper, 2024). "We also found that elevated SLPI levels were positively correlated with renal dysfunction in patients with DKD." (PMID 38501106, 2024). "Moreover, SLPI levels were highly correlated with renal dysfunction in patients with DKD." (PMID 38501106, 2024).
respiratory infections (1 paper, 2021). "SLPI has also been shown previously to play an important role against pathogenic bacteria, including Pseudomonas, during respiratory infections." (PMID 34943813, 2021).
rheumatic diseases (1 paper, 2025). "Targeting the SLPI-associated anti-protease pathways could also potentially be a strategy for ameliorating periarticular inflammation that occurs in some rheumatic diseases." (PMID 40392222, 2025).
urinary tract infection (1 paper, 2024). "In the control group, the majority of the top 20 DEGs were associated with the epithelial cells, including epithelial barrier‐related genes (CLDN4, KRT19, and KRT18), and SLPI, a key gene reported to be localized to bladder epithelial cells and protect against urinary tract infection in mouse model." (PMID 38414668, 2024).
tumor (68 papers, 2009 to 2026). "Conversely, in lung carcinoma contexts (e.g., A549 cells), NE suppresses SLPI secretion, an effect linked to its tumor-promoting function." (PMID 41373782, 2025). "Secretory leukocyte protease inhibitor (SLPI), detectable in a variety of secretions, has been implicated in cancers of the head and neck, associated with tumor progression and anti-viral activity." (PMID 34214131, 2021). "For the underlying mechanisms involved in the suppression of tumor progression by SLPI, numerous studies have focused on the NF-κB signaling pathway." (PMID 31462893, 2019). "Through its anti-protease ability, SLPI safeguards tissues from excessive damage caused by proteolytic enzymes released during inflammation and contributes to extracellular matrix remodeling, thereby influencing the cellular and tumor microenvironment." (PMID 41681959, 2026). "Furthermore, SLPI expression is implicated in shaping the immune landscape that facilitates tumor progression, and in driving epithelial-mesenchymal transition (EMT)." (PMID 41681959, 2026). "While SLPI exerts potent anti-inflammatory and tissue-protective effects, its overexpression in multiple carcinomas is associated with pro-tumorigenic effects, potentially through suppression of anti-tumor immunity and promotion of metastasis." (PMID 41373782, 2025). "Researchers speculated that when SLPI is deficient in anti-protease function, the release of protease secreted by the tumor areas can't be suppressed to degrade the peri-cancerous tissues, thus promoting the spread of tumor cells." (PMID 34975323, 2022). "This suggests that high SLPI expression may predispose to better killing of tumor cells by 5FU-based adjuvant chemotherapy." (PMID 35842496, 2022). "Higher levels of SLPI in the tumor have been associated with reduced metastases in HNC." (PMID 34214131, 2021). "High levels of SLPI have been previously associated with enhanced tumor progression." (PMID 25110884, 2014). "Given that SLPI has been implicated in immune suppression within the tumor microenvironment and systemic immune suppression, these findings support the notion that SLPI may contribute to the reduced immune cell infiltration observed in 3LL cells upon NRF2 activation." (PMID 41035689, 2025). "Interestingly, high tumor SLPI expression has been associated with poor prognosis." (PMID 35842496, 2022). "In this study, we aimed to elucidate the expression and functional role of SLPI in CCA, with a particular focus on tumorigenesis, metastatic behavior, and the formation of tumor-associated blood supply systems including angiogenesis and vasculogenic mimicry." (PMID 41557653, 2026). "Overexpression of SLPI enhanced tumorigenic properties, including proliferation, migration, invasion, and in vivo tumor growth." (PMID 41557653, 2026). "Beyond its canonical role as a serine protease inhibitor, accumulating evidence indicates that SLPI can act as a signaling modulator that promotes tumor cell plasticity, survival, and extracellular matrix remodeling." (PMID 41557653, 2026). "To investigate SLPI’s role in tumor blood supply, we assessed its effects on angiogenesis and vasculogenic mimicry (VMF)." (PMID 41557653, 2026). "And the upregulation of SLPI can accelerate tumor development, promote tumor metastasis and induce angiogenesis." (PMID 40520902, 2025). "One additional cluster was characterized by expression of epithelial markers (KRT1, SLPI) and was almost exclusively derived from one tumor (SCH4)." (PMID 38216553, 2024). "As a pro-tumor factor, upregulated SLPI promotes colorectal tumorigenesis through activation of the MAPK signaling pathway." (PMID 39170693, 2024). "Secretory leukocyte protease inhibitor (SLPI) showed upregulation in the tumour area with immune activation, contributing to the transport of class‐switched immunoglobulin G (IgG) and IgA antibodies." (PMID 39187937, 2024).
tumor (continued). "This are the case with the high expression of CLU and SLPI, upregulated genes in the tumor samples that are correlated to cell migration and invasion capacity, favoring metastasis and therefore resulting in more severe disease." (PMID 36982287, 2023). "Specifically, MMP9, MMP13, MMP11, and CEMIP were positively associated with the tumor immune microenvironment, while SLPI, SLC2A1, SERPINB5, HK2, CEACAM6, and CEACAM5 were negatively associated with the tumor immune microenvironment." (PMID 37234801, 2023). "At this stage, SLPI expression in the primary tumor appears to reflect a biological process which is unfavorable to the tumor and is associated with reduced formation of distant metastases at a later time." (PMID 35842496, 2022). "A number of studies have reported that SLPI plays a signifcant role in the regulation of tumor progression and metastasis." (PMID 34975323, 2022). "We observed SLPI expression in the cytoplasm of the tumor cells; in some tissue cores mainly on the luminal side of the tumor cells and in other tissue cores in the whole cytoplasm of the tumor cells." (PMID 35842496, 2022). "Using the polyclonal antibody, we detected expression of SLPI in the cytoplasm of tumor cells of 96% of CRC patients." (PMID 35842496, 2022). "In the present study, we detected that SLPI was expressed at a lower level in tumor liver tissues compared with non-tumor liver tissues which was closely correlated with poor clinical outcome of HCC patients." (PMID 34975323, 2022). "One immune factor, secretory leukocyte protease inhibitor (SLPI), has been implicated in HNC as a possible marker of tumor progression." (PMID 34214131, 2021). "However, the underlying mechanism of SLPI-mediated tumor cell invasiveness remains largely unknown." (PMID 32742768, 2020). "SLPI has previously been reported by a good number of studies to influence the progression of various cancers, either as a tumor promoter or tumor suppressor." (PMID 31462893, 2019). "During this process, genes such as SOD2, MMP19, SLC2A3, and SLPI were also upregulated, all of which were related to the invasion and migration of tumor cells." (PMID 31487431, 2019). "More importantly, our preliminary study demonstrated that SLPI acts as a tumor suppressor and functionally influences the proliferation and apoptosis of HNSCC cells." (PMID 31462893, 2019). "Serpin peptidase inhibitor clade E member 2 (SERPINE2/protease nexin-1) and secretory leukocyte protease inhibitor (SLPI) are secreted serine protease inhibitors which are overexpressed in a number of cancers and involved in tumor formation." (PMID 28255192, 2017). "SLPI, a member of the Kazal superfamily of serine-proteinases, appears to play a role in tumor growth and metastasis." (PMID 26279647, 2015). "The positive expression of SLPI was positively correlated with the degree of tumor differentiation (P < 0.05)." (PMID 25441765, 2014). "SLPI may also influence the tumor microenvironment by modulating cytokine expression, remodeling the extracellular matrix, and promoting processes such as epithelial-mesenchymal transition (EMT) and vasculogenic mimicry." (PMID 41557653, 2026). "Third, tumor-stroma crosstalk may converge on PI3K/AKT signaling, as SLPI delivered in extracellular vesicles from cancer-associated fibroblasts activates this pathway in other tumors, suggesting a plausible axis to test in CCA." (PMID 41557653, 2026). "Moreover, it has been shown that engrafted tumor cell lines that express low levels of SLPI grow slower in Slpi-/- mice, while tumor cell lines with high SLPI expression form tumors similarly to WT mice." (PMID 40496854, 2025). "SLPI was highly expressed in basal‐like subtypes compared to luminal ones, and its expression was not related to clinical stage and appeared to have a potential impact on the tumor microenvironment and its immune composition." (PMID 40922505, 2025).
tumor (continued). "Moreover, other studies have demonstrated that E6 promotes Akt phosphorylation in HNC cells; however, this effect is inhibited by secretory leukocyte protease inhibitor (SLPI), a tumor suppressor which has shown a decreased expression in HPV-positive HNCs." (PMID 37237486, 2023). "In addition, the expression of SLPI was associated with different stages of tumor development, including the stages of TNM (tumor, node, metastasis), lymph node metastasis, and distant metastasis." (PMID 36595102, 2023). "We suggest that high expression of SLPI may inhibit the infiltration of M2 macrophages, thereby suppressing tumor growth." (PMID 37070095, 2023). "SLPI could silence the neutrophil elastase’s anti-tumor effects, which are immune-related capabilities of attenuating tumorigenesis and attacking distant metastasis." (PMID 36742380, 2023). "Taken together, these results further suggested the anti-tumor activities of SLPI toward HCC." (PMID 34975323, 2022). "We previously hypothesized that SLPI expression may be beneficial for metastatic CRC tumor cells via promotion of immune evasion." (PMID 35842496, 2022). "Furthermore, IRGs associated with tumor progression, including PDGFA, ITPR3, SLPI, TICAM1, and GATA4, were identified." (PMID 36588538, 2022). "In conclusion, our study demonstrated that SLPI has anti-tumor effects both in vivo and in vitro." (PMID 34975323, 2022). "The existing researches have shown SLPI could serve as a tumor regulator to mediate the progression and prognosis of a wide range of cancers." (PMID 34975323, 2022). "By manipulating the expression of SLPI in cultured hepatoma cells and xenografted tumor tissue, we observed that SLPI could inhibit proliferation, migration and invasion capacities of HCC cells." (PMID 34975323, 2022). "In contrast, in the stage prior to distant metastasis formation SLPI expression in the tumor may counteract other tumor cell functions." (PMID 35842496, 2022). "In differentiated tumor cells SLPI expression may reflect a response to the tumor microenvironment, whereas in more aberrant cells SLPI expression may reflect increased metastatic potential." (PMID 35842496, 2022). "Although stage III CRC patients have lymph node metastases, tumor cells need to acquire different functionalities for the formation of distant metastases and therefore the role of SLPI in this stage could be different." (PMID 35842496, 2022). "Interestingly, for some other cancers, SLPI expression level is inversely correlated with tumor progression." (PMID 34975323, 2022). "As a protease inhibitor, it has been suggested that SLPI provides protection to the mucosa and skin against the enzymatic pathways that lead to cancer invasion and progression by preventing tissue degradation from certain tumor proteases." (PMID 34214131, 2021). "In this study, we constructed a recombinant adenovirus expressing EGFR-targeting artificial microRNA and active revCASP3 (Ad-EC), under the control of tumor-specific SLPI promoter, and evaluated its inhibitory effect on HEP-2 cancer cells both in vitro and in vivo." (PMID 32745124, 2020). "Previous studies have shown that SLPI is related to tumor metastasis." (PMID 33381555, 2020). "In addition to the tumor-promoting roles of SLPI, it has also been demonstrated to inhibit tumor progression in a variety of cancer types." (PMID 31462893, 2019). "Then, exogenous secretory leukocyte protease inhibitor (SLPI) was added into the cell culture to investigate whether it could maintain its tumor suppressor effect on E6-expressing HNSCC cells." (PMID 31462893, 2019). "These facts suggested that SLPI might play a critical role in the progression of tumor growth and proliferation in human PDAC." (PMID 25954138, 2015). "A number of recent studies have described a role for SLPI in tumor development and progression." (PMID 25110884, 2014).